CXCR6 (C-X-C motif chemokine receptor 6)
Diseases named in the same sentence as CXCR6 in open-access papers (continued):
Sharing a sentence is not in itself a finding about the gene and the disease.
glioma (18 papers, 2009 to 2025). A benign or malignant brain and spinal cord tumor that arises from glial cells (astrocytes, oligodendrocytes, ependymal cells). "An over-expression of CXCL16 was noted in glial tumor and stroma cells, while CXCR6 expression is more likely associated with glioma-stem cells." (PMID 35269652, 2022). "CXCL16/CXCR6 signaling acted directly on promoting tumor cell growth, migration and invasion by promoting glioma‐associated microglia/macrophages modulation toward a pro‐tumor phenotype, being a critical target for glioma treatment." (PMID 34482648, 2021). "CXCL16 is expressed in human glioma, while the presence of CXCR6 is controversial, likely associated with glioma-stem cells." (PMID 30542347, 2018). "The presence of CXCR6 in GBM is associated with glioma-stem cells." (PMID 32456359, 2020). "Glioma cells release the C-X-C motif chemokine ligand 16 (CXCL16), which differentiates TAMs to the M2 variant by signaling through CXCR6." (PMID 41157253, 2025). "Glioma-secreted CXCL16 binds to CXCR6 on microglia, and the CXCL16-CXCR6 axis mediates the polarization of microglia, promoting a shift to a pro-tumor phenotype and promoting tumor invasion and progression." (PMID 37700840, 2023). "MFAP2 expression was also correlated with chemokine receptors in gliomas, such as CCR3, CCR7, CXCR4, and CXCR6, which were significantly associated with MFAP2 expression in both LGG and GBM." (PMID 36204318, 2022). "CXCL16/CXCR6 axis acts a pivotal part in the pro-tumor microenvironment, and the silencing of CXCR6 reduced the proliferation rate on glioma cells, indicating that CXCR6 plays an oncogenic role in glioma." (PMID 35571062, 2022). "Microglia from glioma-bearing CXCR6-ko mice had lower expression levels of anti-inflammatory genes, compared to glioma-bearing wt mice that suggested CXCL16/CXCR6 axis involvement in the anti-inflammatory programming of microglia." (PMID 36686729, 2022). "As a final point, CXCL16 was demonstrated to be considerably expressed by glial tumor and stroma cells, whereas CXCR6 was found in stem cell fenotype cells." (PMID 35269652, 2022). "While CXCL16 is widely expressed by glioma and glioma stromal cells in vitro and in situ, CXCR6 has been shown to likely be restricted to highly proliferative glioma stem cells." (PMID 34203660, 2021). "The other main functions of CCR5 and CXCR6 signaling include proliferation and invasion of glioma cells." (PMID 34203660, 2021). "To confirm a role for CXCR6 in glioma development also in vivo, we orthotopically implanted GL261shCXCR6 cells, silenced or not with IPTG (+/-IPTG), into the brain of wt mice." (PMID 30542347, 2018). "We also describe that CXCL16/CXCR6 signaling acts directly on mouse glioma cells, as well as human primary GBM cells, promoting tumor cell growth, migration and invasion." (PMID 30542347, 2018). "For the first time we demonstrated that CXCL16/CXCR6 axis plays a role in promoting glioma growth, directly acting on tumor cells." (PMID 30542347, 2018). "From our recent investigations, we know that CXCL16 is highly expressed in different human gliomas, while the corresponding receptor CXCR6 is restricted to a small subset of glioma cells with stem cell characteristics." (PMID 28698473, 2017). "Moreover, we show that CXCL16 produced by glioma cells directly stimulates the CXCR6 expressed by tumor cells, promoting their proliferation, migration and invasion." (PMID 30542347, 2018). "Moreover, by in situ hybridization, it has been shown that CXCR6 is expressed in glioma only on a small population of cells that are positive for markers of embryonic or neural stem cells." (PMID 30542347, 2018). "However, apart from its classical signaling mode in which the proteolytically released chemokine domain would bind to and signal via its receptor CXCR6, we recently discovered an alternate signaling mechanism for transmembrane chemokines in glioma cells which we termed “inverse signaling”." (PMID 27784296, 2016).
glioma (continued). "Especially, CCR5/CCL5 and CXCR6/CXCL16 signaling modulates TAM polarization, as well as the proliferation and invasion of glioma cells." (PMID 37818357, 2023). "CXCL16/CXCR6 signaling acts directly on human primary GBM cells and mouse glioma cells, promoting tumor cell growth, invasion, and migration." (PMID 32456359, 2020). "The presence of CXCL16 derived from glioma cells was observed to promote tumor invasion and proliferation through a chemokine receptor that binds the soluble form of CXCL16, C-X-C chemokine receptor 6 (CXCR6)." (PMID 41157253, 2025). "Considering that CXCL16 specific receptor CXCR6 is diffusely expressed in the brain including in microglia cells, we wanted to investigate the role of CXCL16 in the modulation of microglia cell activity and phenotype, and in the progression of glioma." (PMID 30542347, 2018). "Indeed, a single study previously examining the CXCL16/CXCR6 axis in GBM demonstrated that CXL16 expression in myeloid cells (particularly microglia) allows cells to adopt an anti-inflammatory state and that in the context of glioma, it contributes to immunosuppression." (PMID 38299146, 2023). "We initially demonstrated this mechanism in cultivated malignant human glioma cells, from which we had previously shown to express high levels of CXCL16, but a lack of the corresponding receptor CXCR6." (PMID 27784296, 2016). "Glioma cell lines did not express CXCR3, CXCR4, CXCR6, CX3CR1, but high levels of CXCR7, which is a receptor for CXCL11 and CXCL12 and can mediate G-protein independent signals via arrestin." (PMID 26796342, 2016). "The absence of CXCR6 on glioma cells, but not on other cells of tumor microenvironment, reduces but does not block tumor development, suggesting that other signals are important for tumor progression, and again confirming that CXCL16/CXCR6 signaling acts also on cells of the tumor microenvironment." (PMID 30542347, 2018).
liver cancer (16 papers, 2017 to 2025). An epithelial or non-epithelial malignant neoplasm that arises from the liver. "Previous studies regarding the effect of CXCR6 on liver cancer have revealed that after injection of diethylnitrosamine, the tumor load of CXCR6-deficient mice is markedly higher than that of wild-type mice, and tumor progression is increased." (PMID 34218795, 2021). "Interestingly, activation of NKT cells is also dependent on CXCR6/CXCL16 interaction, as deficiency of CXCR6 or neutralization of CXCL16 cause hepatic cancer to deteriorate." (PMID 36389715, 2022). "In this study, we focused on a receptor abundant on the surface of liver cancer cells called CXCR6, which communicates with signals in the tumor environment and helps cancer cells survive." (PMID 41375019, 2025). "Increased CXCR6 expression has also been observed across several cancers, including renal, prostate, breast, and liver cancers, where it served as a prognostic marker for overall survival." (PMID 39588301, 2024). "Importantly, we also discovered that only certain types of liver cancer cells responded strongly, depending on their specific features related to CXCR6 and β-catenin." (PMID 41375019, 2025). "Inhibition of bile acid (BA)-converting Clostridium species that are responsible for converting primary BAs to secondary BAs can increase the expression of CXCL16 on LSECs to attract the infiltration of hepatic CXCR6+ NKT cells to inhibit liver cancer progression." (PMID 38283696, 2024). "Similarly, abnormally high expression levels of CXCR6 and CXCL16 are found to be closely related to tumor proliferation and metastasis, and have been reported to be associated with human ovarian cancer and the metastasis of liver cancer cells." (PMID 33381455, 2020). "At the protein level, the average percentage of L4-LrNK-FCGR3A (CXCR6+CD16+) cells was 8.53% in the healthy liver, but their proportion in the liver cancer tissues (2.7%) was significantly lower than that in healthy liver tissues, as demonstrated by FACS." (PMID 35856557, 2022). "CXCL16 is highly expressed in many cancers, including ovarian, breast, prostate, colon, and liver cancers, and the expression of CXCL16/CXCR6 correlates with lymph node metastasis in epithelial ovarian carcinoma 52,53." (PMID 31892988, 2020). "In contrast, high expression of CXCR6 and CXCL16 in mammary or liver cancers correlated with reduced proliferation and invasiveness." (PMID 28267793, 2017).
ovarian carcinoma (16 papers, 2010 to 2025). A malignant neoplasm originating from the surface ovarian epithelium. "Tumor-promotive tumor-associated macrophages (TAMs) and the CXCL16/CXCR6 axis have been reported to be correlated with the limited efficacy of chemotherapy in ovarian cancer (OC)." (PMID 37272931, 2023). "Analysis of The Cancer Genome Atlas (TCGA) for ovarian cancer revealed CXCR6 expression to be associated with CD103 and increased patient survival." (PMID 36311728, 2022). "Together, the observations confirm that loss of CXCR6 reduces resident memory responses and the associated protection against ovarian cancer." (PMID 34607898, 2021). "Analysis of TCGA database of patients with ovarian cancer further corroborated this strong association between CXCR6 and CD103." (PMID 34607898, 2021). "Analysis of The Cancer Genome Atlas (TCGA) (ovarian cancer database revealed CXCR6 to be associated with CD103 and increased patient survival." (PMID 34607898, 2021). "Our current study addresses this gap and identified CXCR6 as the predominant chemokine receptor expressed by CD8+ Trm cells in human ovarian cancer, and their presence in tumors is associated with increased survival." (PMID 34607898, 2021). "Further, CXCR6 was found associated with increased survival only with patients with CD8-high ovarian cancer." (PMID 34607898, 2021). "More importantly, the expression of CXCL16 and CXCR6 had been implied to be overexpressed in epithelial ovarian cancer which was closely associated with tumor growth, proliferation, invasion and lymph node metastases." (PMID 30996686, 2019). "In an ovarian cancer model, CXCR6-deficient mice have less TRM in the tumor." (PMID 36311728, 2022). "In head, neck, and lung tumors and ovarian cancer, CXCR6 can promote the recruitment of CD8+ T cells in TME." (PMID 36090326, 2022). "CXCR6, by promoting retention in tumor tissues, serves a critical role in resident memory T cell-mediated immunosurveillance and control of ovarian cancer." (PMID 34607898, 2021). "The role of CXCR6 on antitumor T cells was investigated using prophylactic vaccine models in murine ovarian cancer." (PMID 34607898, 2021). "Chemokine receptor profiling of CD8+CD103+ resident memory tumor-infiltrating lymphocytes in patients with ovarian cancer revealed high expression of CXCR6." (PMID 34607898, 2021). "Using murine prophylactic vaccine models of ovarian cancer, we demonstrate that CXCR6 marks tumor-specific resident memory T cells." (PMID 34607898, 2021). "CXCR6-deficient tumor-specific CD8+ T cells showed reduced retention in tumor tissues, leading to diminished resident memory responses and poor control of ovarian cancer." (PMID 34607898, 2021). "The expression of CXCR6 in epithelial ovarian cancer is significantly higher than that in normal ovarian and benign tissues." (PMID 33829065, 2021). "Our chemokine receptor profiling studies of human ovarian cancer TILs using qPCR, flow cytometry, and confocal microscopy all revealed high expression of CXCR6 on CD8+ CD103+ Trm cells." (PMID 34607898, 2021). "The expression of CXCR6 in ovarian cancer tissues is higher than that in adjacent tissues and is positively correlated with the expression of TNF-α." (PMID 33829065, 2021). "Our studies in both humans and mice strongly indicate that CXCR6 is highly expressed on Trm cells, play a critical role in their localization within tumor tissues, and impart increased protection against ovarian cancer." (PMID 34607898, 2021). "Only two of these genes, IRF-1 and CXCR6, were also found to be differentially expressed in our cohort of 49 serous advanced-stage ovarian cancer patients (P=0.018578 resp." (PMID 20664601, 2010). "Interestingly, in the early stage of ovarian cancer metastasis, mesothelial cells promote peritoneal mesothelial fibroblast transformation by activating CXCR6, thereby promoting ovarian cancer proliferation and peritoneal metastasis." (PMID 33829065, 2021).
ovarian carcinoma (continued). "However, this study obtained an opposite conclusion that the overexpression of CXCR6 was associated with OS, PFS, and PPS of ovarian cancer." (PMID 33829065, 2021). "In ovarian cancer, CXCR6 is highly expressed on TRM‐like cells, and its ligand CXCL16, primarily produced by EpCAM−CD45− stromal cells, facilitates their spatial retention within the tumor microenvironment, suggesting that CXCL16 delivery or CXCR6 engineering may promote TRM accumulation." (PMID 41361844, 2025). "Among different pathological types of ovarian cancers, there were various degrees of expression differences, except for CXCR5 and CXCR6, and the gold change ranged from 1.628 to 2.824." (PMID 33829065, 2021). "Ovarian cancer cell lines OVCAR-3 and SKOV-3 with high expression of CXCR6 have higher migration and invasion abilities." (PMID 33829065, 2021). "The results showed that CXCRs were expressed in both cell membrane and cytoplasm of ovarian cancer tissues, among which CXCR4 expressions were the highest, and CXCR3, CXCR5, CXCR6, and CXCR7 were expressed in different degrees." (PMID 33829065, 2021). "In conclusion, the present study implicates CXCR6 as a critical regulator of residency and persistence of memory CD8+ T-cell responses in ovarian TME, thereby increasing enhanced immunosurveillance and control of ovarian cancer." (PMID 34607898, 2021). "Functional studies in mouse models of ovarian cancer revealed that CXCR6 is a marker of resident, but not circulatory, tumor-specific memory CD8+ T cells." (PMID 34607898, 2021). "CXCR1 and CXCR2 were downregulated in ovarian cancer tissues, while CXCR5 and CXCR6 were not significantly different between ovarian cancer and normal tissues." (PMID 33829065, 2021).
lung carcinoma (15 papers, 2014 to 2025). "Clinically, low CXCR6 expression is significantly associated with poor prognosis in lung cancer patients, while higher CXCR6 levels have been linked to improved outcomes, particularly in lung adenocarcinoma." (PMID 41149503, 2025). "This highlights the potential of CXCR6 as both a prognostic biomarker and a therapeutic target in lung cancer immunotherapy." (PMID 41149503, 2025). "In CXCR6 knockout mice, the probability of metastases originating from either Lewis lung carcinomas or B16 melanoma cells in the liver was enhanced." (PMID 38928238, 2024). "The CXCL16/CXCR6 axis mediated the improved viability and invasion of lung cancer cell lines in vitro." (PMID 38928238, 2024). "Lung cancer cells also highly express CXCL16/CXCR6, which promote lung cancer cell migration and invasion in vitro and bone metastasis in vivo." (PMID 37025604, 2023). "In ovarian and lung cancer, at the protein level, CXCR6 was predominantly expressed on CD8+ TRM as compared with intratumoral effector CD8+ T cells or circulating T cells." (PMID 36311728, 2022). "We present the first study on the prognostic impact of the chemokines CXCL16 and CXCR6 in lung cancer." (PMID 26021984, 2015). "After confirmed the functional existence of CXCL16 and CXCR6 in A549, H292 and 95D cells by FCM and ELISA, we further performed several in vitro experiments to explore the significance of CXCL16-CXCR6 expression in human lung cancer." (PMID 24897301, 2014). "It was demonstrated that similar to CXCL12 and CXCR4, CXCL16 and CXCR6 were also coexpressed in human primary lung cancer tissues." (PMID 24897301, 2014). "In the present study, the expression of CXCL16 and CXCR6 in human lung cancer tissues and lung cancer cell lines, A549, H292 and 95D, was determined by immunohistochemistry and immunocytochemistry respectively." (PMID 24897301, 2014). "After confirming the functional existence of CXCL16 and CXCR6 protein in A549, 95D and H292 cells by ELSA and flow cytometry analysis, we further explored the significance of CXCL16-CXCR6 axis in the biological functions of lung cancer cell lines in vitro." (PMID 24897301, 2014). "Finally, the prognostic relevance of CXCR6 expression has been increasingly recognized in lung cancer." (PMID 41149503, 2025). "However, blocking CXCL16-CXCR6 axis by CXCL16 neutralizing antibody or CXCR6 protein down-regulation only partially blocked the increased invasion of lung cancer cell lines induced by the CM (compared with the control, P<0.01)." (PMID 24897301, 2014). "Therapeutically, the addition of CXCR6 to specific CAR-T cells enhances their intratumoral accumulation and prolongs survival in animal models of pancreatic, ovarian and lung cancer." (PMID 36311728, 2022). "The results clearly demonstrated that not only CXCR6 and CXCR4 (30/33) but also CXCL12 and CXCL16 (19/33) were coexpressed in both human primary lung caner tissues and lung cancer cell lines." (PMID 24897301, 2014). "CXCR6 has been identified as a preferentially expressed chemokine receptor on CD8+ TRM cells following vaccination in murine models, as well as on intratumoral CD8+ TRM cells isolated from human lung cancer specimens." (PMID 41149503, 2025). "In lung cancer, CXCR6 affects the recruitment of antitumor CD8 + T cells to the TME, and low expression of CXCR6 significantly correlates with poor prognosis in patients with lung cancer." (PMID 38698468, 2024). "Given the importance of CXCR6 in lung cancer immunotherapy, we investigated whether the function of CXCR6 is mediated by the CXCL16-CXCR6 axis." (PMID 38698468, 2024). "As a continuation of this work, we showed that CXCR6 was preferentially expressed by CD8+ TRM after intranasal vaccination in mice with a vector targeting DC and also on intratumoral CD8+ TRM derived from human lung cancer." (PMID 36311728, 2022).